FBXL5 (F-box and leucine rich repeat protein 5)
Diseases named in the same sentence as FBXL5 in open-access papers (continued):
Sharing a sentence is not in itself a finding about the gene and the disease.
tumor (12 papers, 2014 to 2026). "These experiments suggest that FBXL5 levels are decreased by IR causing a major stabilization of Snail1 in tumour cell lines." (PMID 24157836, 2014). "In vivo, LGALS3 knockdown markedly increased tumor volume, whereas FBXL5 overexpression reduced tumor growth." (PMID 42093989, 2026). "Currently, both the oncogenic and tumor-suppressive roles of FBXL5 have been found across cancers including colon cancer and HCC." (PMID 35936737, 2022). "In a summary, FBXL5 served as a tumor suppressor in PC carcinogenesis through the ALKBH5–FBXL5–IRP2/SNAI1 axis in an m6A-dependent manner, indicating a potential role of FBXL5 in the diagnosis, prognosis, and target therapy of PC." (PMID 35936737, 2022). "Particularly, we observed that downregulation of FBXL5 in tumor samples correlated with shorter survival time of patients." (PMID 34733841, 2021). "In line with downregulation of FBXL5 in tumor cells of PDAC, we found that both IRP2 and SNAI1 were upregulated." (PMID 34733841, 2021). "Notably, we show here that upon ALKBH5 overexpression, the stabilized FBXL5 further elicited the downregulation of the IRP2 and SNAI1 proteins, both of which are substrates ubiquitinated by FBXL5 and are crucial drivers of tumor progression." (PMID 34733841, 2021). "However, the interaction between FBXL5-mediated iron homeostasis regulation and oncogenic signaling pathways in the tumor microenvironment, as well as how they are coordinated by the global regulatory network of neddylation, requires further experimental investigation." (PMID 41444773, 2025). "In vivo results also demonstrated tumor xenografts shrinkage upon ALKBH5 overexpression, but this effect was weakened when FBXL5 was knocked down." (PMID 39680684, 2025). "In CC cells, FBXL5 and BTG3 function as tumor suppressors and direct downstream targets of miR-20a, and the repression of FBXL5 and BTG3 can restore the invasive and resistant characteristics of CC cells, which was suppressed by iASPP or miR-20a depletion." (PMID 28399926, 2017). "We found that siRNA-mediated knockdown of FBXL5 or BTG3 significantly restored the invasive abilities and reduced the anti-tumor activity of cisplatin in iASPP- or miR-20a-silenced CC cells." (PMID 28399926, 2017). "Taken together, these data indicate that FBXL5 and BTG3 serve as tumor suppressors in CC cells, and miR-20a-FBXL5/BTG3 signaling is responsible for iASPP-induced EMT and cisplatin resistance." (PMID 28399926, 2017). "However, in contrast to normal epithelial tissues, the expression of FBXL5, PSMB2, and PSMD12 was markedly decreased in tumor epithelial cells." (PMID 41444773, 2025). "Therefore, FBXL5-induced degradation of SNAI1 protein and subsequent EMT changes also contributed to hinder tumor progression of PDAC." (PMID 34733841, 2021). "In CRC progression, FBXL5 has shown to induce cell proliferation, growth, tumorigenesis and inhibit cell apoptosis by modulating PTEN/PI3K/AKT signalling and its overexpression resulted in high tumour formation ability." (PMID 31906201, 2019).
cancer (10 papers, 2014 to 2025). A tumor composed of atypical neoplastic, often pleomorphic cells that invade other tissues. "Overexpression of Fbxo9 significantly reduced cancer cell migration compared with the overexpression of Fbxl3, Fbxl5, or Fbxl8." (PMID 38486234, 2024). "Fbxl5 and Fbxo31 were also reported to control Snai1 levels through its ubiquitination, resulting in the inhibition of cancer cell invasiveness." (PMID 33114139, 2020). "In addition, the role of Fbxl5 in cancer was reported in colon, breast and osteosarcoma." (PMID 33114139, 2020). "Then we performed a pan-cancer bioinformatics analysis based on the BioXpress database, to analyze the mRNA expression of FBXL5 and BTG3 in cancer tissues and their paired normal tissues across multiple cancer types." (PMID 28399926, 2017). "Importantly, the high miR-20a expression and the correspondent low FBXL5 and BTG3 expression in cancer tissues correlate with the poor prognosis of the patients in a Kaplan–Meier survival analysis." (PMID 33803151, 2021). "On the other hand, nuclear FBXL5 protein also functions as a ubiquitin ligase of SNAI1, which is a key modulator of the EMT and thus involved in multiple kinds of cancers." (PMID 34733841, 2021). "Among these, FBXL5 and BTG3 have been reported to regulate EMT and cancer metastasis." (PMID 28399926, 2017). "This analysis also indicated a similar negative correlation between high iASPP and low FBXL5/BTG3 expression in various cancer types." (PMID 28399926, 2017). "We currently do not have an in vivo intestinal/colon model that implicit FBXL5 as a potential therapeutic target for cancer stem cells, although an essential role of FBXL5-mediated cellular iron homeostasis in the maintenance of hematopoietic stem cells has already been reported." (PMID 31906201, 2019).
infection (3 papers, 2014 to 2024). The state of being infected such as from the introduction of a foreign agent such as serum, vaccine, antigenic substance or organism. "Furthermore, infection of Myc-FBXL5 almost totally abolished the Snail1-HA stabilization caused by irradiation." (PMID 24157836, 2014). "Infection of shRNAs against eight F-box proteins (FBXL5, FBXW5, FBXO3, FBXO4, FBXO5, FBXO24, FBXO25 and FBXO27) upregulated Snail1 protein levels (at least by 2-fold) compared with parental cells or cells infected with a control shRNA." (PMID 24157836, 2014). "Conceivably, dynamic upregulation of fbxl-5 in response to adverse environmental conditions, which could include reduced food availability or pathogen infection, might tune vitellogenin expression levels to match the energetic resources that are available." (PMID 38946799, 2024).
neurodegenerative disease (2 papers, 2019 to 2021). A disorder of the central nervous system characterized by gradual and progressive loss of neural tissue and neurologic function. "One of the functions of the SCF complex is to eliminate misfolded proteins, and various components of the complex (SKP1, Cullin1, FBXL5, FBXO7, FBXL18, Parkin) have been associated with neurodegenerative diseases." (PMID 34709416, 2021).
hematopoietic diseases (1 paper, 2017). "Suppression of iron regulatory protein 2 (IRP2) accumulation in FBXL5-deficient mouse HSCs restores stem cell function, implicating IRP2 as a potential therapeutic target for human hematopoietic diseases associated with FBXL5 downregulation." (PMID 28714470, 2017). "We finally examined whether FBXL5 deficiency might be associated with human hematopoietic diseases." (PMID 28714470, 2017).
FBXL5 also shares sentences with these, for which no sentence is quoted: Angelman syndrome (1 paper); cervical squamous cell carcinoma (1); head and neck cancer (1); infectious disease (1); Intellectual disability (1); lymphoblastic lymphoma (1); movement disorder (1); pancreatic ductal adenocarcinoma (1); Turner syndrome (1).